CD44 (CD44 molecule (IN blood group))
Diseases named in the same sentence as CD44 in open-access papers (continued):
Sharing a sentence is not in itself a finding about the gene and the disease.
cancer (continued). "Additionally, while we observed reduced lung metastasis associated with CD44 downregulation, further investigation into the role of different CD44 splicing variants across various cancer types would provide a more comprehensive understanding of TGF-β′s impact on metastasis." (PMID 39758992, 2024). "Despite the alternative splicing of CD44, targeting this receptor is an attractive strategy for developing receptor-mediated therapeutics due to the ability of a single HA chain to simultaneously bind multiple CD44 receptors and to signal numerous cancer-associated mechanisms." (PMID 38931956, 2024). "Galectin-9 encoded by LGALS9 could bind to receptor CD44 to regulate anti-cancer immunity." (PMID 38918785, 2024). "The understanding of the mechanisms of alternative splicing and the occurrence of variant isoforms of CD44 is essential not only to a deeper insight into malignant progression but may also provide a new generation of splicing inhibitors as therapies for cancer." (PMID 38106992, 2023). "Interestingly, increased CD44 expression was associated with well-differentiated carcinomas." (PMID 37664387, 2023). "Additionally, CD44 expression can lead to receptor tyrosine kinase signaling, including transforming growth factor beta receptor type 1, and hence it has been associated with cancer cell chemoresistance." (PMID 34951143, 2022). "Notably, we also demonstrated that the disruption of GLUT1 decreases glycolytic activity and thereby depresses the enhanced stemness induced by CD44v10 upregulation, providing a novel mechanism by which CD44 variants confer stem-like properties of cancer cells." (PMID 36243113, 2022). "However, the role of EVs in cancer development and its association with CD44 and CD81 functions remain unclear." (PMID 36193887, 2022). "Furthermore, the overexpression of FOXM1 leads to the acquisition of an EMT phenotype by activating the mesenchymal cell markers ZEB1, ZEB2, Snail2, E-cadherin, and vimentin, which are associated with increased spheroid-forming capacity and cancer stem cell surface markers (CD44 and EpCAM)." (PMID 36613925, 2022). "However, HMMR (in combination with CD44) has been hypothesised to play an important role in cancer-associated fibroblast migration." (PMID 34199452, 2021). "In addition, CD44 is known to be the major receptor for hyaluronan (HA), which is implicated in cell–cell and cell–matrix interactions and is associated with the promotion of cancer metastasis." (PMID 34680456, 2021). "This process releases biologically active substrates, via alternative splice forms of CD44, that generate CD44v3 or v6 isoforms which participate in the transcriptional regulation of genes and proteins associated to signaling pathways involved in the development of cancer." (PMID 33505471, 2021). "CD44+ cancer stem cells may cause cancer cells to be resistant to treatment." (PMID 34804499, 2021). "Therefore, the focus on this specific CD44 isoform variant combined with cancer-related glycan structures could pave the way for new biomarkers in GC." (PMID 31973075, 2020). "Additionally, there is some evidence to suggest that interactions between low molecular mass HA and CD44 may play a role in cancer-associated inflammation." (PMID 32455980, 2020). "However, whether CD44 genetic polymorphisms affect the subtype and the content of these CD44 isoforms in various cancers is worthy of further research." (PMID 32344833, 2020). "Consequently, targeting CD44 using anti-CD44 and/or CD44 variant-specific antibody and/or anti-sense strategies to downregulate CD44 and/or CD44 variants may be a possible choice for the development of new cancer cell-based therapies." (PMID 31293964, 2019). "However, during cancer progression, a loss of expression of all CD44 variants was found." (PMID 30112117, 2018). "One or multiple splice variants and standard CD44 may be expressed in cancer cells." (PMID 28326306, 2017).
cancer (continued). "To investigate whether EMT- and cancer stemness- associated proteins were also regulated by this miR-520b-CD44 molecular axis, we examined the expression levels of these molecules in response to miR-520b and CD44 co-modulations." (PMID 28515423, 2017). "However, the regulatory mechanism involved in the CD44 associated cancer stemness is still unclear." (PMID 28515423, 2017). "Moreover, HA-bound CD44 interacts with several other membrane-associated proteins, including tyrosine kinases, matrix metalloproteases (MMPs), integrins and drug efflux transporters, reinforcing activities that drive cancer progression." (PMID 28883992, 2017). "Therefore it is relevant to quantify the association of CD74 and CD44 in cancer cells." (PMID 29190904, 2017). "Because of the important role that CD44 plays in cancer invasion and metastasis, it has been suggested that the expression of CD44 or certain CD44 variants could serve as valuable candidates for early detection, or as a prognostic predictor for gynecologic malignancies." (PMID 28070170, 2017). "Interestingly, elevated CD44 expression is associated with enhanced invasiveness of cancer cells." (PMID 27165430, 2016). "In conclusion, the results indicate that CD44 polymorphism rs13347 acts as a risk factor for cancer, especially in Chinese, while the minor allele of polymorphism rs11821102 may be associated with a decreased susceptibility to cancer." (PMID 28000766, 2016). "However, CD44 expression has long been associated with cancer cell metastasis." (PMID 27165430, 2016). "Standard CD44 is the smallest and most abundant isoform, whereas the other variants are expressed in a cell-specific manner (e.g., on epithelial cells or keratinocytes), as well as in multiple pathologies, including rheumatoid arthritis, diabetes, multiple sclerosis, and cancer." (PMID 26904028, 2016). "Moreover, CD44 was associated to proliferative activity of cultured canine cancer cells." (PMID 25884842, 2015). "Fourth, although inflammation-associated cancers accumulate activated immune cells with upregulated transferrin receptors and CD44 variants and may take up the Tf-PEG-PEI-nanoparticles, there will be no deletion of CD44 variant because the promoter is not lymphocyte specific." (PMID 26448753, 2015). "Highly expressed CD44 variants could make interesting candidates for selective cancer targeting." (PMID 24122205, 2014). "This may be due to a loss of CD44 splice control mechanisms in malignant tumors." (PMID 24122205, 2014). "Interestingly, a cloned Buthus martensi hyaluronidase (BmHYA1) down-regulated CD44 (a hyaluronic acid-ligand transmembrane glycoprotein involved in cell–matrix connections) in a cancer cell line, suggesting that a variant of cancer cells can be modulated by external venom hyaluronidase treatment." (PMID 23658852, 2013). "Additionally, we have presented some evidence that the analysis of isolated CD44 and CD24 immunoexpression or the CD44/CD24 immunophenotypes could give a prognostic informations associated to clinicopathologic features Salivary Gland Malignant Neoplasms." (PMID 23419168, 2013). "CD44v6, the v6 variant of CD44, is mainly expressed in a subset of adenocarcinomas and the expression of adhesion molecule CD44v6 could well reflect the invasiveness and adhesiveness of malignant tumor cells." (PMID 23420582, 2013). "However, others found a reduction of CD44 variants in tumors of patients with advanced carcinoma." (PMID 23476138, 2013). "However, whether CD44 variants can serve as cancer stem cell makers is waiting for further investigations." (PMID 23217022, 2012). "Thus, CD44 and Musashi-1 may be useful as diagnostic markers for the detection of precursor lesions such as IM and dysplasia, as well as for the prediction of cancer risk in patients with IM in GC." (PMID 21829201, 2011).
cancer (continued). "For several other cancers, while several studies have shown that overexpression of CD44s and its splice variants, particularly CD44v6, are associated with poor prognosis and metastasis, others have shown that downregulation of CD44 expression correlated with adverse outcome." (PMID 21819617, 2011). "Overall, our label-free live-imaging approach demonstrates that cancer and immune cells share both common and unique features in endothelial adhesion under flow, and allows identification of CD44 and HA as key mediators of PDAC cell arrest." (PMID 41495248, 2026). "An increase in EMT and CD44, the cancer stem cell marker, with pregnancy levels of PRL dose, was also confirmed." (PMID 41501898, 2026). "TGF-β also supports cancer stem cells (CSCs) by promoting the expression of CD44 and CD133 and suppresses MHC-I/II and recruits Tregs/MDSCs." (PMID 41476776, 2026). "Functionally, ATN significantly inhibited proliferation, induced apoptosis, and suppressed tumorsphere formation and CD44+/CD24- cancer stem cell (CSC) population in CRPC cells." (PMID 42158813, 2026). "On the basis of the relevant differences in the TAMs and cancer cell stemness, we then conducted a spatial analysis to examine the distances of TAMs in relation to CD44+ cancer cells." (PMID 41545340, 2026). "HA is a ligand for adhesion receptor CD44, which is overexpressed in various cancers and inflammatory diseases." (PMID 41885409, 2026). "In HCC, β-catenin further downregulates E-cadherin (an inhibitory factor of β-catenin), upregulates N-cadherin and vimentin (pro LGR5 and CD44 also maintain cancer stem cell (CSC) population and resulting in chemoresistance and recurrence." (PMID 41476776, 2026). "Both pharmacological inhibition with Box5 and genetic ablation of RHOA effectively abrogated GNG10-induced oncogenic phenotypes and the upregulation of cancer stem cell markers (CD44, CD133, OCT4, Nanog, SOX2)." (PMID 42252561, 2026). "PDA exposure also induced epithelial–mesenchymal transition (EMT), upregulated cancer stem cell markers (CD44, CD117, CD133, Sox2, Oct4, and Nanog), and elevated expression of metastasis- and chemoresistance-associated molecules (MMP-2, MMP-9, MDR1, and MRP1)." (PMID 41596307, 2026). "Through this study, we have identified characteristics of TME in patients experiencing recurrence after CCRT treatment, showing heightened interaction between SPP1‐positive macrophages and cancer cells via CD44 or ITGB1." (PMID 41466485, 2026). "In terms of cancer cell stemness, MIF inhibition in MASLD led to a reduction in CD44+ or ALDH+ or CD44+/KLF4+ cancer cells." (PMID 41545340, 2026). "Spatial analysis revealed there was more distant proximity between TAMs and CD44+ cancer cells upon MIF inhibition." (PMID 41545340, 2026). "While CD44 isoform usage and epithelial splicing regulators ESRP1/2 are well-characterized in cancer-associated epithelial-mesenchymal transition (EMT), their regulation across physiological, non-transformed identity states remains less well defined." (PMID 41751394, 2026). "Reduced OPN also diminished CD44 activation, impairing EMT-associated cancer stemness via JAK2/STAT3 and FAK/STAT3 pathways." (PMID 41356204, 2026). "The spatial proximity between TAMs and CD44-positive cancer cells further supports the role of MIF-CD44 signaling in shaping the metastatic niche." (PMID 41545340, 2026). "Hyaluronic acid (HA) modification enables the targeting of CD44-overexpressing cancer cells, enhances biocompatibility, provides controlled drug release, and prolongs systemic circulation." (PMID 41754914, 2026). "This method, demonstrated with CD44+ EVs as a model, showed satisfactory utility for clinicalblood samples and versatility with other EV targets, providing reliableguidance for cancer diagnoses and management strategies." (PMID 40720603, 2025). "As a cell-surface glycoprotein, CD44 is recognized as an important marker of cancer stemness, metastasis, and ECM interactions." (PMID 40282339, 2025).
cancer (continued). "As a candidate for sensing HA, CD44, a well-known receptor for HA and a recognized biomarker for cancer stem cells, can be considered." (PMID 41461315, 2025). "Computational stemness scores and cancer stem cell immunophenotypes—such as CD44 with xCT/SLC7A11 expression—consistently predict poorer survival." (PMID 41562911, 2025). "For cancer invasion, CD44 is a type I transmembrane glycoprotein known to facilitate cell adhesion and migration in a variety of cancers." (PMID 40699920, 2025). "CD44, a multifunctional cell surface protein, has emerged as a pivotal regulator in cancer stem cell (CSC) biology, orchestrating processes such as stemness, metabolic reprogramming, and therapeutic resistance." (PMID 40259468, 2025). "The possibility of modulating the CD44-HA interaction with a pharmacological inhibitor has therefore been recognized as an emerging anti-cancer strategy." (PMID 41155181, 2025). "In the case of hypoxia, the recent studies by Makela and colleagues showed that populations of CD44+ cancer stem cells become PS-positive and can be targeted by novel PS-directed payloads." (PMID 41198619, 2025). "CD44, also known as the hyaluronan receptor, has various implications for cell survival, proliferation, mobility, and is often dysregulated in cancer, leading to metastasis, fibrosis and therapy resistance." (PMID 40140675, 2025). "To investigate this further, we focused on the expression of CD44, a well-established marker of cancer stem cells." (PMID 40849307, 2025). "Consistently, previous studies have demonstrated that CD44 and integrin β1 are co-enriched and colocalized in plasma membrane microdomains where they cooperate in regulating cancer cell motility." (PMID 40342488, 2025). "The results show that the RL extract stimulates cancer cell death by decreasing the CD44/24 ratio, and increasing apoptotic activity." (PMID 39888200, 2025). "Other signature genes, including ITGA5, ANGPT2, and CD44, have recognized roles in cancer progression and are already under investigation as therapeutic targets." (PMID 41374933, 2025). "Given the importance of CD44 as a cancer biomarker, it has been reviewed in several articles, many of which discuss its role as a biomarker and therapeutic target." (PMID 41440277, 2025). "The epithelial OC origin of the PDC2 and PDC3 samples was confirmed by the expression of OC-specific markers PAX8 and CD24, epithelial makers MKI67, EPCAM, KRT8 and KRT18 and cancer stem cell markers such as CD44 and ROR1." (PMID 39482470, 2025). "CD44 is one of the most recognized markers of cancer stem cells, a small subset of cells responsible for cancer initiation, progression, and metastasis." (PMID 41440277, 2025). "Upon incubation with cancer cells, the nano-assemblies were internalized via a CD44 endocytosis-mediated mechanism, with the extent of internalization depending on the HA conjugate content." (PMID 40142123, 2025). "During the EMT process, the post-transcriptional regulations specifically alternative splicing of CD44 occur and impart a trans-differentiation process that modulates the metastatic potential and chemoresistant properties of cancer cells." (PMID 40260304, 2025). "CD44 is also recognized as a cell surface marker of cancer stem-like cells (CSCs) in various carcinomas." (PMID 41009730, 2025). "Their enhanced properties not only validate the potential of this approach for sequential cancer therapy in CD44-positive cancers but also pave the way for future clinical translation and further optimization in cancer treatment." (PMID 40284532, 2025). "Expression levels of cancer stem cell (CSC) marker genes Lgr5, Smoc2, Axin2, Rnf43, and CD44 were markedly reduced in Prrc2a‐deficient tumors induced by AOM‐DSS treatment." (PMID 39582289, 2025). "In this study, the HA moiety enabled the selective accumulation in CD44-overexpressing cancer cells, offering a promising strategy to reduce off-target toxicity." (PMID 40429669, 2025).
cancer (continued). "After successful conjugation, the DOX-NP conjugate was coated with hyaluronic acid (HA) to allow for better targeting since HA has a high affinity to CD-44 glycoproteins that are usually overexpressed in cancer cells." (PMID 39852748, 2025). "SATB1 siRNA-encapsulated immune liposomes binding to CD44 antibodies target cancer-initiating cells (CICs), reducing CIC proliferation by about 80% and reducing the CIC population by about 60%." (PMID 40071088, 2025). "The functionalization of N-GQDs with HA served in the targeting of the CD44 cancer cell receptor overexpressed in HeLa cells and played a key part in the regulation of cell proliferation and survival." (PMID 40429669, 2025). "Specifically, ligand–receptor pairs, such as MIF (CD74–CXCR4) and MIF (CD74–CD44), indicate the importance of CD44 in epithelia, cell proliferation, and certain cancers." (PMID 40605976, 2025). "Mass spectrometry in conjunction with aptamer binding assays across various cancer cell lines identified CD44 as the cellular target of sTN58." (PMID 40342488, 2025). "The efficacy and versatility of CD44-targeted nanoparticles in cancer treatments are shown by their capacity to effectively deliver conventional chemotherapeutic agents such as PTX." (PMID 41367861, 2025). "CD44 is a transmembrane glycoprotein expressed in different isoforms and is involved in several key cancer processes, such as carcinogenesis, progression, and resistance to therapy." (PMID 39977830, 2025). "CD44, a transmembrane glycoprotein that is essential to cell structure, is often used as a marker for cancer stem cells (CSCs)." (PMID 41367861, 2025). "For example, in breast cancer, CD44+/CD24+ enriched cells displayed cancer stem-like features while CD133 is frequently used in colon and brain tumors and CD90 in liver tumors." (PMID 41228380, 2025). "CD44 protein is highly expressed on the surface of cancer cells and plays a crucial role in cancer progression." (PMID 40670469, 2025). "CD44, a cell surface glycoprotein abundantly expressed in cancer stem cells, promotes cancer invasion and metastasis mainly by increasing cell motility." (PMID 40624675, 2025). "CD44 fared prominently in the current study, having roles in long-term responses to injury and fibrosis and being a prognostic marker for various cancers, including ccRCC." (PMID 40558504, 2025). "We investigated the dynamics of the cancer stem cell marker CD44 during dormancy induction and exit." (PMID 40430044, 2025). "Hyaluronic acid (HA) is a natural and biocompatible polysaccharide that selectively binds to CD44, enabling intracellular drug delivery to cancer cells." (PMID 40264886, 2025). "CD44 has been shown to have a significant impact on cancer cell invasion and metastasis, as well as on essential biological processes such as lymphocyte homing, hematopoiesis, inflammation, wound healing, and apoptosis." (PMID 41367861, 2025). "The expression of putative cancer stem cell markers (CD44, CD133, and CD166) was evaluated using antibody staining and flow cytometry." (PMID 41303421, 2025). "Measuring soluble CD44 in various biological liquids can provide a practical and valuable tool for cancer diagnosis and treatment monitoring." (PMID 41440277, 2025). "Research indicates that cancer cells with high CD44 expression exhibit increased treatment resistance and metastatic potential." (PMID 40888184, 2025). "Consistently, TFAP2A enhanced the protein levels of cancer stem cell markers and stemness-related genes, including CD44, CD133, NANOG, OCT-4A and SOX2." (PMID 40727938, 2025). "CD44 has been recognized as a marker for CSCs and a therapeutic target for a variety of cancers.CD44 is involved in several immune response processes." (PMID 40642092, 2025). "Several studies have emphasized the significant potential of CD44-targeted nanocarriers in the field of cancer therapy." (PMID 41367861, 2025).